UGCG (UDP-glucose ceramide glucosyltransferase)
Diseases named in the same sentence as UGCG in open-access papers (continued):
Sharing a sentence is not in itself a finding about the gene and the disease.
infection (continued). "Bates and coworkers demonstrated a role for UGCG in infections by specific bunyaviruses at a post-internalization step and importantly, that study ruled out the need for UGCG for virus binding or internalization." (PMID 32032363, 2020). "One recent study employing a haploid genetic screen revealed a role for UGCG in infections by specific bunyaviruses but not in those by other viruses tested." (PMID 30918081, 2019). "Indeed, we found that infection by C. rodentium, not by L. monocytogenes, downregulates hepatic UGCG expression, supporting the idea that C. rodentium replication in the intestine can impact the expression of this host lipid-synthesizing enzyme." (PMID 39567665, 2024). "Infection study indicated that SPT-KO and UGCG-KO cells showed no detectable defects in the cell surface binding (4°C) or internalization (37°C) of HRTV." (PMID 36920967, 2023). "The siRNAs targeting UGCG both inhibited rVSV-SFTSV infection relative to the non-targeting siRNA, with siUGCG #1 resulting in over 80% reduction in infection (p<0.0001, Student’s t-test)." (PMID 28388693, 2017).
cardiovascular diseases (1 paper, 2025). "UGCG is one of the key molecules involved in metabolic remodeling and has become a key therapeutic target in tumors and cardiovascular diseases, driving clinical drug development." (PMID 41049486, 2025).
UGCG also shares sentences with these, for which no sentence is quoted: Gaucher disease type 1 (4 papers); cyst (3); diabetes (3); lung carcinoma (3); Niemann-Pick disease type C (3); Parkinson disease (3); Sandhoff disease (3); Alzheimer disease (2); atherosclerosis (2); kidney failure (2); leukemia (2); Obesity (2); polycystic kidney disease (2); synucleinopathy (2); adult-onset Still disease (1); Allergy (1); amyloid (1); Anxiety (1); Ataxia (1); autism (1); autosomal dominant polycystic kidney disease (1); cholangiocarcinoma (1); chronic kidney disease (1); chronic myeloid leukemia (1); Cognitive impairment (1); COVID-19 (1); ductal breast carcinoma (1); epilepsy (1); Farber disease (1); GM1 gangliosidosis (1).
A further 32 diseases each share a sentence with UGCG in 1 paper.